SNORA22C (small nucleolar RNA, H/ACA box 22C)
Gene: Small nucleolar RNA gene on chromosome 7 (65,065,999 to 65,066,132, forward strand). Ensembl gene ENSG00000207344.
Gene Ontology:
Biological process: RNA processing
Cellular component: nucleolus
Homologues: Orthologues: rat Snora22c (87% identical), mouse Gm23245 (86% identical). Paralogues in human: SNORA22 (99% identical), SNORA22B (95% identical).